VIM (vimentin)
Diseases named in the same sentence as VIM in open-access papers (continued):
Sharing a sentence is not in itself a finding about the gene and the disease.
cervical carcinoma (continued). "In line with this, our knock down of SDHC or SDHD in cervical cancer cells increased the expression of vimentin, ZEB1 and TWIST, but reduced e‐cadherin." (PMID 37899663, 2024). "Our results showed that vimentin expression is significantly increased in early-stage (p = 0.02) and late-stage (p = 0.02) cervical cancer compared to samples with in situ cancer and those used as controls." (PMID 38606999, 2024). "Vimentin was found to be upregulated by treatment of cervical cancer cells with TGF-β; IL-6; and with chemokine CCL20." (PMID 36766756, 2023). "In this study, we found that TNF-α and TGF-β1 in the cell model of advanced cervical cancer upregulated N-cadherin and Vimentin proteins, which contributed to the increased proliferation and invasion of CaSki cells." (PMID 37445768, 2023). "IL-9, a T-helper 9 cytokine, reduced the expression of N-cadherin and vimentin in cervical cancer cells and increased expression of E-cadherin." (PMID 36766756, 2023). "In oral and cervical cells, PIR gene silencing with small interfering RNA (siRNA) was shown to increase E-cadherin transcripts as well as reduce Vimentin, Slug, Zeb and Snail transcripts in oral and cervical cancer cells." (PMID 38033031, 2023). "Its presence in cervical cancer is associated with larger tumor size, shorter disease-free survival, and the expression of VIM (vimentin)." (PMID 36992411, 2023). "shRNA-mediated silencing of ESM1 downregulated the expression of Vimentin, N-Cadherin and Slug, while upregulating E-Cadherin in cervical cancer cells." (PMID 36522312, 2022). "Our Western blotting experiment revealed that APMAP knockdown inhibited the EMT process of cervical cancer cells, which decreased the protein expressions of snail, N-cadherin and vimentin, and increased the protein E-cadherin." (PMID 34539899, 2021). "A de–regulation of Wnt signaling was also reported for liver and cervical cancer, associated with a reduction of EMT markers such as SNAI1, SNAI2, ZEB1 or VIM in cervical cancer–derived cell lines." (PMID 34062997, 2021). "RIPK4 promoted invasion and metastasis of cervical cancer cells by inhibiting expression of 'vimentin, MMP2 and fibronectin which were pivotal molecules of epithelial-mesenchymal transition process." (PMID 33487072, 2021). "Next, we examined the expression of EMT-related proteins, including E-cadherin, N-cadherin, vimentin, ZEB1, twist, and snail, to explore the underlying mechanism by which FAM83A promotes the invasion of cervical cancer cells." (PMID 34659522, 2021). "In summary, our present study highlights the importance of a signaling pathway, in cervical cancer, with a significant association between CAIX, PFKFB4, and the EMT proteins E-cadherin and vimentin." (PMID 33803236, 2021). "Knockdown of circAMOTL1 decreased SIK2, p-AKT, N-Cadherin, Vimentin, Slug, Snail, Twist, and upregulated E-Cadherin expression in cervical carcinoma cells." (PMID 33344445, 2020). "We also demonstrated that up‐regulation of C16orf74 can rescue the inhibitory role HAND2‐AS1 overexpression has on cervical cancer cell proliferation, migration and invasion, as evidenced by promoted expression of N‐cadherin, vimentin, MMP‐2 and MMP‐9." (PMID 32314545, 2020). "The miR-31-3p mimic significantly increased the expression level of miR-31-3p in cervical cancer Caski cells and significantly increased the mRNA and protein levels of E-cadherin, while it downregulated the mRNA and protein levels of Vimentin and Snail." (PMID 31776419, 2019). "In our study, we conducted immunohistochemistry staining to determine the expression of Ki-67, E-cadherin and vimentin, the results showed that Ki-67 and vimentin was decreased in cervical cancer tissues while E-cadherin was increased when we knockdown XIST." (PMID 30858762, 2019). "The reorganization of VIFs was also examined in human cervical carcinoma HeLa cells that express both vimentin and keratin 18 (a type I cytokeratin)." (PMID 30696956, 2019).
cervical carcinoma (continued). "Additional cancers witness vimentin overexpression including certain types of lymphomas, endometrial carcinomas, papillary thyroid carcinomas, cervical cancers, clear-cell renal-cell carcinomas, and central nervous system tumours." (PMID 30248895, 2018). "To determine if the impact of N. brasiliensis L3 antigen on cervical cancer cell migration was associated with changes in markers of EMT, we assessed the expression of E-cadherin, N-cadherin and vimentin by western blotting." (PMID 30069018, 2018). "MMP1 is overexpressed in cervical cancer, and knockdown of MMP1 reduced the proliferation and migration of cervical cancer cells, while expression of epithelial marker E-cadherin increased and expression of mesenchymal marker Vimentin decreased." (PMID 30283446, 2018). "Occupancy of LSD1 was detected specifically at the transcription start site of Vimentin in cervical cancer cells." (PMID 27894088, 2017). "Specifically, we examined fluctuations of EMT‐related markers, fibronectin, vimentin, and cytokeratin, following transfection of CaSki cells, a small bowel mesentery metastatic cervical cancer cell line, with siTUG1." (PMID 28088836, 2017). "The important finding of this study is that Vimentin is one of the genes through which LSD1 promotes the EMT in cervical cancer." (PMID 27894088, 2017). "We found that Vimentin expression is closely correlated with Ki67 expression in cervical cancer tissues (P = 0.037)." (PMID 28912668, 2017). "Our multivariate analysis also suggests that Vimentin is an independent marker for survival in cervical cancer patients." (PMID 28912668, 2017). "Our data show that Vimentin can serve as an independent prognostic marker for cervical cancer patients with primary surgery." (PMID 28912668, 2017). "Our study showed that miR-31 induced EMT via regulating BAP1 expression in cervical cancer cells and marked the expression of E-cadherin downregulated and N-cadherin and vimentin upregulated." (PMID 29159179, 2017). "Here, we demonstrated that Vimentin expression can act as an independent predictive factor for patients with cervical cancer, providing important guidelines for the management of cervical cancer patients." (PMID 28912668, 2017). "Here, we confirmed that knockdown of CCL19 suppressed EMT through the downregulation of vimentin, consistent with upregulation of E-cadherin in cervical cancer cells." (PMID 29088748, 2017). "In contrast, we found that overexpression of LSD1 increased Vimentin expression, while knockdown of LSD1 attenuated Vimentin expression at the protein level in cervical cancer." (PMID 27894088, 2017). "In conclusion, we proposed a novel mechanism whereby ectopic expression of LSD1 promoted the EMT in cervical cancer, and discovered intriguing functions of HPV16 E7 and LSD1 in the promotion of Vimentin transcription in cervical cancer." (PMID 27894088, 2017). "Our results suggest that TUG1 knockdown activates cytokeratin expression and decreases the expression of vimentin and fibronectin in cervical cancer, partly explaining the metastasis‐related mechanism in this disease." (PMID 28088836, 2017). "The current findings concluded a possible role of vimentin in the development and progression of cervical cancer and vimentin marker will be useful in the diagnosis and grading of cervical cancer." (PMID 27190522, 2016).
cervical carcinoma (continued). "It discovered that TRIM62 expression was positively correlated with α-Catenin expression (r = 0.736, P = 0.001), whereas negatively correlated with Vimentin expression (r = -0.612, P = 0.003) in randomly selected cervical cancer sections." (PMID 27793172, 2016). "Detailed and more studies are needed to assess vimentin and cytokeratin expression in cervical cancer and its correlation with clinical outcome of the patients." (PMID 27190522, 2016). "This case control study aimed to interpret the expression of vimentin and cytokeratin proteins in the development and progression of cervical cancer and its correlation with clinicopathological features." (PMID 27190522, 2016). "Our findings showed that expression of vimentin was 40% and expression pattern was increased according to grade of cervical cancer cases and these differences were statistically significant." (PMID 27190522, 2016). "This study aims to interpret the expression of the vimentin and cytokeratin protein in the development and progression of cervical cancer and make relationship between vimentin and cytokeratin protein expression based on clinicopathological characteristics." (PMID 27190522, 2016). "Intermediate filaments protein family has shown a role in the diagnosis of various cancers, but a few studies are available about the vimentin and cytokeratin roles in the cervical cancer." (PMID 27190522, 2016). "The current finding suggested a possible role of vimentin in the development and progression of cervical cancer and vimentin marker will be helpful in the diagnosis and grading of cervical cancer." (PMID 27190522, 2016). "Intermediate filament (IF) protein family such as cytokeratin and vimentin has been suggested to play a role in the diagnosis of cervical cancer." (PMID 27190522, 2016). "To further explore the underlying mechanism of RIPK4 in promoting the migration and invasion of cervical cancer cells, we measured Vimentin, MMP2 and Fibronectin mRNA expression in RIPK4-siRNA-transfected cells and control cells." (PMID 26148476, 2015). "The newly identified miR-720/Rab35 axis provides a molecular mechanism for abnormal cell migration in cervical cancer cells via its effects on the expression of an epithelial marker, E-cadherin, and a mesenchymal marker, vimentin." (PMID 26413265, 2015). "Depletion of Sam68 inhibits migratory and invasive potential of cervical cancer cells as well as the expression of vimentin and fibronectin, possibly through suppressing the Akt/GSK3β/Snail pathways." (PMID 26356073, 2015). "Overexpression of AEG1 resulted in downregulation of E-cadherin and upregulation of N-cadherin and vimentin, thus increasing invasive capability of cervical cancer cells." (PMID 26356073, 2015). "Here, we showed that the transfection of Gankyrin markedly up-regulates Vimentin, Twist2, β-catenin and down-regulates E-cadherin in cervical carcinoma cells." (PMID 24751719, 2014). "In vitro, the transfection of Gankyrin resulted in markedly up-regulating of Vimentin, β-catenin and Twist2, as well as down-regulating of E-cadherin in cervical carcinoma cells." (PMID 24751719, 2014). "The proteins with the highest betweenness were 14-3-3ζ, vimentin and vinculin, part of our central core of cervical cancer proteins, which is consistent with their role as bait proteins." (PMID 21696634, 2011). "Similar to the proteomic study of cervical carcinomas, but in contrast to the findings in other carcinomas, we found a downregulation of vimentin in both vaginal and cervical carcinoma, suggesting alternative pathways for epithelial–mesenchymal transition." (PMID 19367286, 2009). "Of the 17 downregulated proteins, 6 different proteins showed low expression in both vaginal and cervical carcinoma compared with normal vaginal tissue (calreticulin, tropomyosin 2 beta, vimentin, gelsolin, vinculin and filamin)." (PMID 19367286, 2009).
cervical carcinoma (continued). "In both vaginal and cervical carcinoma there was a downregulation of vimentin, filamin, tropomyosin 2 (TM2 beta) as well as vinculin." (PMID 19367286, 2009). "Expression of vimentin has been postulated to play a role in invasiveness and metastasis in cervical carcinoma." (PMID 18769604, 2006). "Additionally, increased levels of E-cadherin (epithelial marker) and reduced N-cadherin and Vimentin (mesenchymal marker) were observed in bergenin-treated cervical cancer cells." (PMID 38961106, 2024). "Moreover, Vimentin regulates CSC responses to fractionated radiation exposure in cervical cancer, highlighting its role in the survival and proliferation of these stem cells." (PMID 39766136, 2024). "Moreover, ESM1 depletion upregulated E-Cadherin, but downregulated N-Cadherin, vimentin, and Slug in human cervical cancer cells and SiHa xenografts tissues." (PMID 36522312, 2022). "JNK/c-Jun signalling promoted the invasive potential of cervical cancer cells and was required for the expression of the epithelial to mesenchymal transition (EMT)-associated transcription factor Slug and the mesenchymal marker Vimentin." (PMID 33303976, 2021). "Vimentin, which serves as an important intermediate filament protein in mesenchymal cells, plays a key role in the metastatic growth and invasion of tumor cells, including cervical carcinoma cells." (PMID 32185181, 2020). "Furthermore, Twist and Vimentin were significantly elevated in patients who had cervical carcinoma with an aggressive FIGO stage (both P < 0.001), a high histological grade (P = 0.003 and P = 0.016; respectively), and lymph node metastasis (both P < 0.001)." (PMID 32185181, 2020). "AC-GlcNAc-conjugated branched PEI that can interact with HeLa cells, cervical cancer cells, but not with vimentin-deficient HeLa cells is presumed to be optimal for the specific recognition of cell-surface vimentin." (PMID 32645972, 2020). "NKX6.1 could recruit the BAF155 coactivator to enhance the mRNA level of E-cadherin and recruit the RBBP7 (retinoblastoma binding protein 7) corepressor to repress that of vimentin in cervical cancer." (PMID 32707737, 2020). "In our previous studies, we demonstrated that NKX6.1 is a bifunctional transcription factor that suppresses EMT in cervical cancer cells by increasing the expression of the epithelial marker E-cadherin and decreasing the expression of the mesenchymal marker vimentin." (PMID 32707737, 2020). "Moreover, Snail was a superior prognosis factor compared to Slug, ZEB1, Twist, Vimentin, and Survivin in cervical carcinoma." (PMID 32185181, 2020). "Knockdown of circAMOTL1 could reduce SIK2, p-AKT, N-Cadherin, Vimentin, and upregulated E-Cadherin expression of cervical carcinoma cells in vivo." (PMID 33344445, 2020). "Moreover, increased N‐cadherin and vimentin expression has been linked with high cell migration in tumours, further supporting the migration‐inhibitory role of HAND2‐AS1 in cervical cancer." (PMID 32314545, 2020). "Moreover, decreased migratory ability was observed in cervical cancer cells derived CSCs along with down-regulated expression of N-cadherin and Vimentin and up-regulated E-cadherin after treatment with 10, 20, and 30 μM zoledronic acid, respectively." (PMID 30791957, 2019). "Here we make use of several cervical cancer cell lines to demonstrate that exposure to antigens from the hookworm N. brasiliensis significantly reduces cervical cancer cell migration and global expression of vimentin and N-cadherin." (PMID 30069018, 2018). "Vimentin may be modified directly or indirectly by other transcription factors by different mechanisms in cervical cancer cells." (PMID 27894088, 2017). "In our study, the decreased HOXA10 expression and increased HOXB13 expression were associated with reduced E-Cadherin and enhanced Vimentin expression, proposing the need for further studies to establish HOXA10 and HOXB13 as biomarkers of metastasis in cervical cancer." (PMID 28402266, 2017).
cervical carcinoma (continued). "We found that ectopic expression of LSD1 in cervical cancer cells promoted invasion and metastasis in vitro and in vivo, reduced the expression of the epithelial marker E-cadherin, and induced the expression of the mesenchymal marker, Vimentin." (PMID 27894088, 2017). "Present data extend prior work and indicate that S100A7 drives upregulation of EMT markers N-Cadherin, Vimentin, and Fibronectin and loss of epithelial markers E-cadherin, thereby inducting EMT, promoting cervical cancer cell migration and invasion by inducing EMT." (PMID 28212564, 2017). "We speculated that this is one of the mechanisms whereby LSD1 promotes Vimentin expression in cervical cancer." (PMID 27894088, 2017). "Zeb1 also induced the upregulation of vimentin in cervical cancer." (PMID 26356073, 2015). "In the present study, we showed that overexpression of miR-720 leads to a reduction of E-cadherin and an increase of vimentin protein levels in cervical cancer cell lines, which indicates that miR-720 can induce EMT in cervical cancer cells and promote cell migration." (PMID 26413265, 2015). "As the hallmarks of EMT, the up-regulation of Vimentin, Twist2, β-catenin and the down-regualation of E-cadherin caused by the transfection of Gankyrin forcefully indicated Gankyrin’s facilitation effect towards EMT of cervical carcinoma." (PMID 24751719, 2014). "In addition, our data showed that silencing NEDD9 decreased Vimentin expression and increased E-cadherin expression in cervical cancer cells, and vice versa." (PMID 24058594, 2013). "Vimentin was found down-regulated in vaginal and cervical carcinoma compared to normal tissue." (PMID 21711556, 2011). "Additionally, the methylation degree of its promoter region increases, suggesting that VIM could serve as a significant molecular marker for the progression and infiltration of cervical cancer." (PMID 41153737, 2025). "Given that virtually all cervical cancer cases are attributable to high-risk HPV types infection, our finding that AM significantly increased vimentin gene expression in cervical cancer cells suggests that this xanthone could help to prevent HPV viral infection." (PMID 36769377, 2023). "Interestingly, knocking down KAT2B could increase N-cadherin together with Vimentin expression in cervical cancer cells but decrease ZO-1 expression." (PMID 34130593, 2021). "Importantly, our data suggest that positive Vimentin expression may serve as a biomarker to predict a poor prognosis in cervical cancer patients and provides important insights into the design of novel therapeutic strategies to treat cervical cancer patients." (PMID 28912668, 2017). "To elucidate the correlation between CXCL17 expression and EMT in cervical cancer, we performed immunostaining patterns of CXCL17 and relevant EMT markers, including E-cadherin, vimentin, and snail." (PMID 41496085, 2026). "In cervical cancer cells, COL10A1 upregulation promotes proliferation, migration, and EMT processes through activation of N-cadherin and Vimentin via TGF-β/Smad signaling." (PMID 41303526, 2025). "According to the available evidence, miR-223 suppresses the metastasis of cervical cancer cells, preventing the process of EMT by augmenting E-cadherin and α-cadherin and reducing the mesenchymal marker vimentin." (PMID 39968362, 2024). "This study aimed to evaluate the protein expression of vimentin, S100A4, αSMA, FAP, and MMP9 in mesenchymal stem cells (MSC)-CAF cells, as well as in cervical cancer samples." (PMID 38606999, 2024). "Here, the expression of E-cadherin, Vimentin, and SNAIL had a relevant correlation with the overall survival of 691 patients with cervical cancer." (PMID 39061137, 2024).